ADAMTS2 (ADAM metallopeptidase with thrombospondin type 1 motif 2)
Diseases named in the same sentence as ADAMTS2 in open-access papers (continued):
Sharing a sentence is not in itself a finding about the gene and the disease.
Marfan syndrome (2 papers, 2017 to 2018). A disorder of the connective tissue. "Many genes encoding collagen, Timps and other proteins known to be involved in connective tissue diseases such as EDS and Marfan syndrome, including Adamts2, Fbn1 and Fbn2, had more than a 4-fold decreased expression in Zeb2-cKO fibroblasts compared with wild-type fibroblasts." (PMID 28422173, 2017). "Some of the down-regulated genes identified in the DNA array analysis involve those responsible for hereditary connective tissue disorders, including collagens and ADAMTS2 for EDS and fibrillin-1 for Marfan syndrome." (PMID 28422173, 2017).
melanoma (2 papers, 2017 to 2020). A malignant, usually aggressive tumor composed of atypical, neoplastic melanocytes. "ADAMTS2 (a disintegrin and metalloproteinase with thrombospondin type 1 motif 2) was overexpressed in melanomas, compared to melanocytomas." (PMID 28743863, 2017). "THBS2, COL1A1, ADAMTS2 resulted significantly up-regulated in the group of melanomas compared to melanocytomas (P < 0.05, Mann–Whitney)." (PMID 28743863, 2017). "Indeed, it resulted quite appealing the fact that such positive association did occur with high expression of other ADAMTS proteases (ADAMTS2, ADAMTS4, ADAMTS5, ADAMTS9, ADAMTS12 and ADAMTS14) that definitively implied a key role of these proteases during melanoma progression." (PMID 32230715, 2020).
mesothelioma (2 papers, 2013 to 2015). A usually malignant and aggressive neoplasm of the mesothelium which is often associated with exposure to asbestos. "Most of these SNPs were located in regions reported to harbor aberrant alterations in mesothelioma (SLC7A14, THRB, CEBP350, ADAMTS2, ETV1, PVT1 and MMP14 genes), causing at most a 2–3-fold increase in MPM risk." (PMID 23626673, 2013).
myopia (2 papers, 2018). "These included FBN1, ADAMTS2 and TGFB2 which associate with connective tissue disorders (Marfan, Ehlers-Danlos and Loeys-Dietz syndromes), and the LUM-DCN-KERA gene complex involved in myopia, corneal dystrophies and cornea plana." (PMID 29760442, 2018).
osteosarcoma (2 papers, 2012 to 2022). A usually aggressive malignant bone-forming mesenchymal neoplasm, predominantly affecting adolescents and young adults. "Our RT-qPCR results showed that FN1, COL1A2, COL1A1, and ADAMTS2 were downregulated both in osteosarcoma and Ewing's sarcoma tissues compared to normal tissues." (PMID 35578666, 2022). "Besides this, ADAMTS2 is also regulated by TGF-β1 at transcriptional level, which induces an 8-fold increase in ADAMTS2 mRNA levels in MG-63 human osteosarcoma cells in a dose- and time-dependent manner, without affecting RNA stability." (PMID 24213506, 2012).
tendinopathy (2 papers, 2013 to 2023). "In regard to the expression of metalloprotease-encoding genes, increased expression of MMP2, MMP14, MMP16, ADAMTS2, ADAMTS3 as well as downregulation of MMP10 has also been found in tendinopathy." (PMID 38001919, 2023). "MMP2, MMP3, MMP8, ADAMTS2, ADAMTS4, ADAM12 and collagen type I expression were regulated in a similar manner in tendinopathy compared to the current study." (PMID 23830915, 2013).
acute myocardial infarction (1 paper, 2025). Necrosis of the myocardium, as a result of interruption of the blood supply to the area. "Considering the involvement of ADAMTS2, -3, and -14 in procollagen maturation and the role of ADAMTS13 in von Willebrand factor processing, the expression of several ADAMTS enzymes was investigated in acute myocardial infarction." (PMID 40837410, 2025).
adenoma (1 paper, 2009). A neoplasm arising from the epithelium. "Except for NR2F2 (p<0.954), all genes were differentially expressed not only between the three subclasses of adenomas (t-test, p<0.05), but also between the four groups of follicular tumors (F-tests, p<0.05 for ADAMTS2, CABIN1, ALDH13, USP13; p = 0.06 for KRTHB5)." (PMID 19893615, 2009).
Alzheimer disease (1 paper, 2025). A progressive, neurodegenerative disease characterized by loss of function and death of nerve cells in several areas of the brain leading to loss of cognitive function such as memory and language. "Also, the inactivation of Reelin by ADAMTS2 may be a pathogenic process since reduced Reelin levels were linked with worse Alzheimer's disease pathology in animal models." (PMID 40837410, 2025). "Currently, no clear mechanistic link is known between ADAMTS2 expression and Alzheimer's disease pathology, but dysregulation of the ECM may affect the blood–brain barrier, which could be involved." (PMID 40837410, 2025).
amoebiasis (1 paper, 2022). "The prime module in protein-protein interaction network of DEGs, including ADAMTS2, COL10A1, COL1A1, COL1A2, COL8A1, BGN, and SPP1, was enriched in protein digestion and absorption, ECM-receptor interaction, focal adhesion, PI3K-Akt signaling pathway, and amoebiasis." (PMID 35726219, 2022).
Arthritis (1 paper, 2025). Inflammation of a joint. "OLAH was connected to ADAMTS2 in both responders and nonresponder networks; the ADAMTS family are involved in extracellular matrix remodeling and linked to arthritis." (PMID 40415615, 2025).
asthma (1 paper, 2019). "rs11741099 (p-value 2.93 × 10− 6) is intronic to ADAMTS2; the ADAMTS protein family is proposed to play a role in asthma." (PMID 31533690, 2019).
atherosclerosis (1 paper, 2022). A disease characterized by the build-up of fatty material and calcium deposition in the arterial wall resulting in partial or complete occlusion of the arterial lumen. "Many atherosclerosis-related genes, such as ADAMTS2, ECM1, and USP18, showed changes in their expression." (PMID 35806463, 2022).
atopic dermatitis (1 paper, 2021). "Finally, the peculiar atopic dermatitis-like skin phenotype of mice deficient in both ADAMTS2 and ADAMTS14 also points to yet to be discovered new substrates of these two related enzymes." (PMID 33816558, 2021).
cognitive deficits (1 paper, 2025). "Conversely, the downregulation of genes like NPY, CSPG5, VGF, ADAMTS2 and GPC2 among others, in astrocytes and other cell-types points to impaired neuroprotective mechanisms and compromised synaptic function contributing to cognitive deficits." (PMID 41282152, 2025).
colon cancer (1 paper, 2020). "ADAMTS2 is highly expressed in GC and colon cancer and is closely related to distant metastasis and the prognosis of colon cancer." (PMID 32884571, 2020).
colorectal tumour (1 paper, 2019). "Kaplan Meier survival curve showed the expression of HLAB, 14-3-3β, ADAMTS2, LTBP3, NME2 and JAG2 on colorectal tumour cells associated with CRC specific survival." (PMID 30679934, 2019).
cryptorchidism (1 paper, 2023). The failure of one or both testes of a male fetus to descend from the abdomen into the scrotum during the late part of pregnancy. "Male Adamts2-KO and Adamts16-KO mice are infertile and are associated with a marked decrease in testicular sperm and cryptorchidism, respectively." (PMID 37656189, 2023).
fibrous dysplasia (1 paper, 2021). A genetic, non-inheritable disorder caused by osteoblastic differentiation defects that result in the replacement of bone marrow and trabecular bone by fibrous stroma and immature bone. "Conversely, the upregulated expression of ADAMTS2 has been documented in the genomic assessment of fibrous dysplasia, which is characterised by overproduction of the ECM specifically in bone." (PMID 33563616, 2021).
gastric adenocarcinoma (1 paper, 2022). "Altogether, our bioinformatics analysis study identified six upregulated DEGs (ADAMTS2, COL10A1, COL1A1, COL1A2, COL8A1, and BGN) between gastric adenocarcinoma and normal tissues based on four different microarray datasets." (PMID 35726219, 2022).
glaucoma (1 paper, 2024). Increased pressure in the eyeball due to obstruction of the outflow of aqueous humor. "In this line, ADAMTS2 encodes a procollagen proteinase that plays a crucial role in the cleavage of fibrillar procollagens types I-III and type V, involved in the recessively inherited Ehlers–Danlos syndrome type VIIC, which manifest ocular alterations, including glaucoma in a few patients." (PMID 38891949, 2024).
Hennekam syndrome (1 paper, 2020). Hennekam syndrome is characterized by the association of lymphoedema, intestinal lymphangiectasia, intellectual deficit and facial dysmorphism. "In contrast, phenotypes in Ehlers–Danlos syndrome and Hennekam syndrome patients completely differed and involved different organs, although ADAMTS2 and ADAMTS3 possess the same procollagen N-propeptidase domains." (PMID 32183147, 2020).
Kawasaki disease (1 paper, 2024). A rare inflammatory disease characterized by an acute febrile, systemic, self-limiting, medium-vessel vasculitis primarily affecting children. "Plasma concentrations of ARG1, CCL20, CD163, CORIN, CXCL9, PCSK9 and ADAMTS2 were quantified in MIS-C (n = 22), Kawasaki disease (n = 23), definite bacterial (n = 28) and viral (n = 27) disease and healthy controls (n = 8)." (PMID 38359342, 2024).
lung carcinoma (1 paper, 2018). "We additionally identified statistically significant mutations in the metalloproteinases ADAMTS2 (15%) and ADAMTS12 (20%), and in GAS7 (12%) and NTM (10%) (Q < 0.01, Methods section), which so far have not been reported as significantly mutated in any other lung cancer subtype." (PMID 29535388, 2018).
lung fibrosis (1 paper, 2025). "In the peripheral blood of SSc‐ILD patients, upregulated genes including S100A8, S100A12, ADAMTS2, IFNG, and SERPINB2 were identified, which have been linked to the progression of lung fibrosis." (PMID 40165483, 2025).
lymphedema (1 paper, 2022). Excess fluid collection in tissues, causing swelling. "The absence of ADAMTS2 or ADAMTS14 does not involve massive edema in our mouse models, suggesting that mutations in these genes should not be responsible for primary lymphedema." (PMID 35316211, 2022).
male infertility (1 paper, 2024). The inability of the male to effect fertilization of an ovum after a specified period of unprotected intercourse. "However, in addition to having fragile skin due to abnormal collagen structures, Adamts2 KO homozygous mice have been genetically linked to male infertility." (PMID 38871984, 2024).
maxillary deficiency (1 paper, 2022). "Among these SNPs, a heterozygous missense variant (NM_014244: c.3506G>T) in exon 22 of ADAMTS2 was identified to be associated with maxillary deficiency." (PMID 36142585, 2022). "Collectively, these data showed that ADAMTS2 (c.3506G>T: p.G1169V) may confer susceptibility to risk of skeletal Class III malocclusion with maxillary deficiency." (PMID 36142585, 2022). "This indicated that low expression of ADAMTS2 may lead to craniofacial anomalies and maxillary deficiency." (PMID 36142585, 2022). "In this study, we identified a missense variant c.3506G>T in ADAMTS2 and hypothesized that it was responsible for skeletal Class III malocclusion with maxillary deficiency in a Han Chinese family." (PMID 36142585, 2022). "In conclusion, our study identified a missense variant (NM_014244: c.3506G>T) in exon 22 of ADAMTS2 associated with susceptibility to skeletal Class III malocclusion and maxillary deficiency and proved that ADAMTS2 may be related to craniofacial development in vitro and in vivo." (PMID 36142585, 2022).
memory impairment (1 paper, 2022). "As a result, 3 DEmRNAs from CCI with memory impairment model rats (ATF3, C1QC, and CD68) and 13 DEmRNAs from SNI and CCI models (ADAMTS2, BCL6B, CLCF1, RBP1, and TPBG, among others) overlapped with SNI and CCI models, respectively." (PMID 35547819, 2022).
psychosis (1 paper, 2019). "Previous data strongly associated the levels of deregulated ADAMTS2 expression in peripheral blood mononuclear cells (PBMCs) from patients at first episode of psychosis (up) as well as in clinical responders to treatment with antipsychotic drugs (down)." (PMID 31740729, 2019).
thyroid cancer (1 paper, 2022). "Five survival‐related genes, TMEM63C, COL5A1, LOXL1, ADAMTS2, and LYSMD3 were identified; the expression of COL5A1 and LOXL1 was upregulated in PTC tissues and may be related to OS and PFS of thyroid cancer patients." (PMID 35152572, 2022).
Umbilical hernia (1 paper, 2022). Protrusion of abdominal contents through a defect in the abdominal wall musculature around the umbilicus. "For example, mutations in ADAMTS2 are responsible for dermatosparactic type Ehlers-Danlos Syndrome (type VIIC), typified by extreme skin fragility, joint laxity, and umbilical hernia." (PMID 36584111, 2022).
uterine infection (1 paper, 2009). "The uterine infection was also associated with a marked upregulation of several ADAM and ADAMTS metalloproteases, primarily ADAMTS2, ADAMTS5, ADAMDEC1 and ADAM28." (PMID 19956711, 2009).
cancer (29 papers, 2005 to 2026). A tumor composed of atypical neoplastic, often pleomorphic cells that invade other tissues. "In many cancers, the presence of dysregulated ADAMTS2 expression was associated with worse outcomes, but mechanistic insight is generally lacking." (PMID 40837410, 2025). "Using Kaplan-Meier survival curve and log-rank analysis showed that patients whose tumor loss of ADAMTS2 showed significantly shorter cancer survival than those whose tumors expressed ADAMTS2." (PMID 30679934, 2019). "There is also emerging evidence for a role for ADAMTS2 in complex disorders, including cancer and cardiovascular and neurodegenerative disease." (PMID 40837410, 2025). "ADAMTS2 is a procollagen N-proteinase and functions as a key regulator in cancer progression and prognosis." (PMID 40226355, 2025). "Evaluation of the potential substrates and processes that depend on ADAMTS2 is needed in each cancer type and stage to investigate exactly how ADAMTS2 influences tumor progression." (PMID 40837410, 2025). "Adamts2/ADAMTS2 silencing in either mouse or human stellate cells significantly reduced stellate‐led invasion of cancer cells." (PMID 37929635, 2024). "Cancer development and progression are linked to ADAMTS (a disintegrin and metalloproteinase with thrombospondin motifs) family genes, among which ADAMTS2, 4, and 8 have been shown to have antitumor angiogenesis effects." (PMID 37089260, 2023). "We labeled cell types as endothelial cell (Endothelial, gene expression of PLVAP, KDR, PTPRB) and cancer associated fibroblasts cell (CAFs, gene expression of FAP, MMP11, PDGFRB, SFRP2, PDGFRA, ADAMTS2)." (PMID 37065499, 2023). "The role of ADAMTS2 in cancer remains poorly understood; however, the impact of collagen metabolism is well characterized." (PMID 36922933, 2022). "In particular, Adamts1 expression was markedly increased, whereas Adamts2 and -8 expressions, which are presumably important in cancer cell invasion, increased in the later stages of differentiation." (PMID 31297611, 2020). "Some members (ADAMTS2, 4, 6, and 14) are shown to be manifestly upregulated in cancer tissues, whereas others (ADAMTS1, 5, 8, 9, 10, 13, 15, and 18) are downregulated." (PMID 27463966, 2016). "How ADAMTS2 affects cancer progression thus appears to be type-, stage-, or organ-specific, and further research is required to elucidate the role of ADAMTS2 in different cancers." (PMID 40837410, 2025). "The present work identified a pattern of ADAMTS2 differential hypermethylation in heavy smoker subjects in comparison with controls in two neighboring CpGs corresponding to the cg02599361 and cg10208897 Illumina probes in the cancer-free subset, located in CpG islands in the gene body of ADAMTS2." (PMID 37509437, 2023). "Studies have shown that ADAMTS2 expression is abnormally increased in a variety of cancers." (PMID 35879877, 2023). "Interestingly, ADAMTS12 has been shown to have both pro- and anti-tumorigenic activities, while very little is still known about the role of ADAMTS2 in cancer." (PMID 27128408, 2016). "Interestingly, ADAMTS2 has been found to be upregulated in cancer." (PMID 37509437, 2023). "In addition, it is necessary to analyze the expression of ADAMTS2 in various human cancers and to analyse whether the vascularization status of these cancers is affected in anyway by this ADAMTS family member." (PMID 24213506, 2012). "Some cancer cells that acquire a mesenchymal phenotype (such as HS578T, an epithelial breast cancer cell line) do express significant amounts of ADAMTS2." (PMID 40837410, 2025). "Members of the ADAMTS family, such as ADAMTS2, ADAMTS5, ADAMTS12, and ADAMTS15, can act as cancer suppressors or promoters." (PMID 33921267, 2021). "Remarkably, ADAMTS2 was found differentially hypermethylated in heavy smokers without a diagnosis of cancer in two consecutive probes cg05575921 (p = 3.13 × 10−7) and cg10208897 (p = 1.36 × 10−5)." (PMID 37509437, 2023).
cancer (continued). "Furthermore, DMPs of AHRR, ADAMTS2, and FAM184 genes passed the sensitivity analysis for cell composition as follows: For the cancer-free subset, cg04450456 for FAM184B, cg02599361 for ADAMTS2." (PMID 37509437, 2023). "Members such as ADAMTS2, ADAMTS5, ADAMTS12, and ADAMTS15 act as cancer suppressors or promoters." (PMID 33921267, 2021). "In general, cancer cells are of epithelial origin and do not express ADAMTS2." (PMID 40837410, 2025). "However, the downregulation of ADAMTS2, ADAMTS14, MMP11, and MMP7, metalloproteases that help in cancer cell invasiveness by dissolving the ECM components, could prevent cancer invasive potential." (PMID 37834191, 2023). "Besides, these genes, ADAMTS2, KRT9, KRT13, LY6D, had been reported in a variety of cancers." (PMID 35237592, 2022). "Further, this gene was not differentially methylated in the cancer-diagnosed subset; therefore, future studies could explore whether an increase in DNA methylation in the CpG islands of ADAMTS2 could be adaptative or protective for cancer development in heavy smokers." (PMID 37509437, 2023).